CD44 (CD44 molecule (IN blood group))
Diseases named in the same sentence as CD44 in open-access papers (continued):
Sharing a sentence is not in itself a finding about the gene and the disease.
tumor (continued). "The coexpression on PSA-/low cells of other stem cell markers, such as CD44, ALDH1, and alpha2beta1 integrin, enabled purifying of a subpopulation of cells very enriched in tumor-initiating cells." (PMID 31366128, 2019). "Therefore, modulation of the radiosensitivity of these cells could be exclusively ascribed to genetic reprogramming/dedifferentiation due to production of CD24−/low/CD44+ stem-like cells in the tumor through epigenetic changes induced by epithelial mesenchymal plasticity." (PMID 29805752, 2018). "In tumor xenografts combination treatment with GSI and doxorubicin led to better tumor control–by reducing CD44+/CD24low population." (PMID 30515368, 2018). "Tumor-initiating cells (TICs), also known as cancer stem cells (CSCs), are a small subpopulation of cells in the tumor which can be recognized by several cell surface markers, such as CD133, CD24, CD44, and Bmi-1." (PMID 30081498, 2018). "This is illustrated by the surprisingly strong signal of CD44 and EMT in the primary tumor with considerably less expression in the metastasis." (PMID 29693014, 2018). "To cross-validate the results of the IPA®, we set out to confirm the identification and topology of CD147, CD44, and CDH17 depicted in tumor invasion and tumor metastasis networks." (PMID 29899869, 2018). "Tumour infiltrating ILC were found to show an activated phenotype with higher expression of MHC-II, KLRG1, early activation marker CD69 and CD44." (PMID 29587679, 2018). "RTK signaling in tumor and stromal cells plays a critical role in the regulation of both CD24- and CD44+ and ALDH+ve CSC phenotypes." (PMID 29455658, 2018). "The stemness‐associated genes were analysed using RT‐qPCR, and the results showed that the mRNA levels of Nanog, Sox2, Oct4, CD44, CD133, ABCB1, ABCC1, ABCG2 and Notch1 were significantly increased in RCC tumour spheres compared with parental cells." (PMID 30246456, 2018). "Specific molecules including CD34, CD44, CD166, ALDH1, and EpCAM that are expressed in a variety of tumor cells are considered as the primary biomarkers for the identification of CSCs." (PMID 30515411, 2018). "The expression levels of OPN in tumour microenvironment are regulated by CSCs, and, in turn, OPN modulate CSC phenotype via binding with CD44+ cells in promoting tumour progression and metastasis." (PMID 29506506, 2018). "We next analyzed the relationship between the degree of CD44 and VEGF expression in the tumor periphery and pathological features on MRI and clinical outcomes." (PMID 30210550, 2018). "In these tumors, a part of tumor cells co-express other tumor stem cell markers, such as CD133 and CD44." (PMID 30060526, 2018). "Following the first clinical report on CD44 expression in T-ALL, very few clinical-translational approaches were performed to test the value of CD44 as a marker either in tumor expansion or its relevance in the role of T-ALL outcome." (PMID 30430079, 2018). "Because CSCs show tumor seeding ability and resistance to conventional therapies, we examined expression of established CSC markers such as CD44 and aldehyde dehydrogenase (ALDH) activity after CDDP treatment." (PMID 29515788, 2018). "Reduction of expression of a secreted glycoprotein, versican, which is thought to facilitate the CD44–HA interaction, in EOC cells, resulted in reduction of tumor formation by individual cells and abrogation of metastatic ability of spheroids." (PMID 30445726, 2018). "Expression of HA receptors CD44 and RHAMM is required for migration of these tumor cells, and we predict that these receptors also mediate HA-dependent, highly motile CAF subsets." (PMID 29868579, 2018). "Delta Np-63 directly regulates CD44 expression which potentiated EGFR activation and the expression of ABCC1 multidrug transporter gene which contributed to tumor cell proliferation and chemoresistance in HNSCC." (PMID 29747682, 2018).
tumor (continued). "We demonstrated that GFAP/CD133+CD90+/CD44+ EPN cells maintained key histopathological and growth characteristics of the original patient tumor." (PMID 29774098, 2018). "CD44, also known as phagocytic glycoprotein 1 (PGP-1) is a tumor stem cell marker and receptor for hyaluronan, osteopontin (OPN), collagens, and matrix metalloproteinases (MMP) in various tissues." (PMID 29361725, 2018). "Both studies showed expansion of the CK5+/CD44+ CSC population with an increase in colony formation and in vivo tumor initiating capacity." (PMID 29600163, 2018). "The expression of CD44 and CD24 is closely correlated with tumorigenesis, tumor progression, metastasis, and chemotherapy resistance." (PMID 28290053, 2018). "For example, MES GBMs (red arrows) were enriched for CAV1, CD44, CD63, RAB27A, SDCBP and SMPDL3A, while PN (blue arrows) tumours contained higher levels of transcripts for ANXA6, CD81, hnRNPA2B1, YBX1 (RNA binding proteins) and RAB35." (PMID 30034643, 2018). "In the present study, we showed that Hedgehog inhibitor increased the sensitivity for anti-cancer drugs and decreased expression of CD44, c-Myc and Nanog likely through the inhibition of GLI-1 in tumor ALI organoids." (PMID 29642386, 2018). "CD44 ligation with an antibody induces PI3K/Akt signaling in tumor cells, and the interaction between CD44 and HA promotes the survival of tumor cells and alveolar macrophages." (PMID 29684048, 2018). "IL-12-LNP treatment was associated with reduced tumor burden and increased infiltration of activated (CD44+) immune cells such as helper CD3+ CD4+ T cells into the tumor." (PMID 30458889, 2018). "Circulating tumor cells (CTCs) potentially have CSC phenotype and CD44 is considered as its biomarker." (PMID 29747682, 2018). "Consistently, CD44, OAS3, ISG15, STAT1, and WNT5A were significantly upregulated whereas KIT was significantly downregulated in tumor compared to normal in GSE13861." (PMID 30134903, 2018). "Because intra-tumor heterogeneity in ALDH activity and CD44 is often depleted in established cancer cell lines, three OSCC patient-derived xenografts (PDXs) were used instead to establish a feeder-assisted primary culture system." (PMID 29507668, 2018). "Likely, the GFAP/CD133+CD90+/CD44+ EPN cells infiltrated the normal brain parenchyma and have the best chance of escaping surgical resection and of becoming a source of tumor recurrence." (PMID 29774098, 2018). "The results also demonstrated that positive expression of CD44 in CAC was positively correlated with invasion, tumor differentiation, LNM stages, and TNM stages." (PMID 30021598, 2018). "CSCs express a set of shared and unique stem cell markers, including CD44 and CD133, that are characteristic for different tumor types." (PMID 30241339, 2018). "In another study, tumors with stem cell markers, CD44+/CD24–/Lin– and ALDH1, grown as mammospheres showed an increased capacity for tumor initiation in xenograft models." (PMID 30542507, 2018). "Through binding to cell receptors integrin αVβ3and CD44, OPN not only promotes tumor cell survival, proliferation, migration, and invasion, but also acts on ECs to stimulate tumor angiogenesis and metastasis." (PMID 29435158, 2018). "CD44, hyaluronic acid receptor, plays important roles in cell-cell interactions, cell adhesion, invasion/metastasis and is expressed on HCC tumor-initiating cells." (PMID 29899840, 2018). "We investigated the tumor-initiating capacity of the two types of cells that underwent EMT process and checked the expression pattern of CD44." (PMID 29339729, 2018). "This, in turn, changed the percentage of tumor cells with certain CD44/CD24 expression patterns and changed the percentage of tumor-infiltrating immune cells." (PMID 29925435, 2018). "Next, we assessed the ratio of CD44+CD24-/low cells, the subpopulation that have been demonstrated to adopt stem-like phenotypes and tumor-initiating potential." (PMID 30555330, 2018).
tumor (continued). "This group showed very high values in not only the P/C ratios for CD44 but also the relative amounts of CD44 mRNA; they also showed relatively low amounts of VEGF expression in the tumor periphery." (PMID 30210550, 2018). "This CD44+/CD90+ cell subpopulation was located on the periphery of tumor nests and adjacent to CD90+ stroma, being defined as an invasive tumor front." (PMID 29949609, 2018). "And it also dramatically delayed the in vivo tumor initiation and diminished the tumor sizes of CD133/CD44+ cells from Huh7." (PMID 30064482, 2018). "Apart from this, the expression level of CSCs‐related proteins:CD44, ALDH1, KLF4, SOX2 and EMT‐related proteins: Slug, Vimentin were also remarkably elevated in mice SCCHN tumour than that in wild‐type normal tongue tissue." (PMID 29193723, 2018). "In breast cancers, tumor cells undergoing EMT gain CSC properties, including the ability to self-renew and tumorigenicity, and exhibit a CD24−/low/CD44+ phenotype." (PMID 29805752, 2018). "We also found that CD44- and ALK4-mediated signals are both required for optimal tumor growth in immunodeficient hosts." (PMID 30061637, 2018). "In brief, besides contributing via EMT to the release of tumor cells from the primary tumor mass, CIC are engaged in metastatic settlement, which is supported by CD44/CD44v6." (PMID 30211160, 2018). "We next looked at the surface expression of CD24 and CD44 by flow cytometry, in which the CD24-/CD44+ population is indicative of potential tumor initiating cells (TIC) with invasive and drug resistance capabilities." (PMID 29879129, 2018). "miR-34a-induced reduction of the CD44+/CD133+ cells were accompanied by reduced number and size of tumor sphere formation." (PMID 29747682, 2018). "Metformin delayed a tumor growth in a patient-derived-xenograft mouse model and decreased the self-renewal ability of the gastric CSC which highly express CD44 and Sox2." (PMID 29747682, 2018). "CD44 expression was only detected in MCF7-277-ihRNA2 cells, suggesting that these cells had the properties of tumor-initiating." (PMID 29423076, 2018). "Corresponding with our results of enhanced anchorage-independent growth, CXCL1 also increased the expression of CD44, CD326 and CD133, well-known cancer stem cell markers in tumor spheroids." (PMID 30115896, 2018). "More specifically, BCSCs (CD44+/CD24−/low) were shown to be resistant to radiation (compared to non- CD44+/CD24−/low mono-layer cultures), and contributed to tumor recurrence after fractionated radiation." (PMID 30515368, 2018). "Here, we showed that VDAC1 silencing in A549 cell-derived tumours resulted in reduced expression of lung-specific CSC markers, such as ALDH1, KLF4, SOX2, CD133, CD44, CD144, EPCAM, Oct3/4 and Nanog." (PMID 30544833, 2018). "Upon serial passaging in mice, this subset of cells was able to generate new tumors with both CD44+CD24−/low populations as well as phenotypically diverse populations of non-tumorigenic cells, recapitulating the complexity of initial tumor." (PMID 29671772, 2018). "Tumor ALI organoids consisted of epithelial and stromal cell components and they contained many CD44 and LGR5-positive cells." (PMID 29843359, 2018). "HA, together with its receptor (CD44) and degradation enzymes (HYAL-1, etc.), acts as a carcinolytic agent, suppressing tumour growth and metastasis and this is evidenced by accumulation of HA and its associated degradation enzymes within malignant tumours." (PMID 30966217, 2018). "Interrupting this crosstalk affects tumor growth and apoptosis resistance, where EGFR ligation initiates via the STAT3 pathway CD44 transcription." (PMID 30211160, 2018). "We extensively investigated the expression of CD44 and VEGF in both the core and periphery of the tumor in 13 patients." (PMID 30210550, 2018). "Remarkably, CD133+/CD44+ cells with high-OPN generated tumors earlier and their tumor sizes were larger than the controls." (PMID 30064482, 2018).
tumor (continued). "“Tumor debulking” by docetaxel resulted in an increased BCSC population, quantified using ALDH+/CD133+/CD44+." (PMID 30515368, 2018). "The authors verified the superiority of M-CTX-Fc by comparing U251MG-P1 cells (CD44+) with CD44-negative cells (SKBR3) in cellular uptake, in vitro cytotoxicities and in vivo tumor growth inhibition." (PMID 30619758, 2018). "EZH2 plays a role in tumor invasiveness, colony formation and migration and are related to the expression of CSC-related genes (CD44, KLF4, OCT4 and ABCG2)." (PMID 30072631, 2018). "Different subsets of circulating tumor cells were determined on the basis of the expression of EpCAM, CD45, CD44, CD24, and N-Cadherin using flow cytometry." (PMID 29565320, 2018). "Compared to CD44- tumor cell subsets, higher CD47 expression was observed in CD44+ tumor stem cells." (PMID 29029546, 2017). "High expression of CD44 was found to correlate with EMT, which describes the transition of cells from an epithelial to a mesenchymal phenotype that plays a crucial role in tumour proliferation, invasion, and metastasis." (PMID 29281661, 2017). "Syndecan-1 (CD138), MUC-1 (CD227) CD45, CD34, and the putative cancer stem cell markers CD15, CD24, CD44, and CD133 surface expression were evaluated on CSF floating tumor cells." (PMID 28399903, 2017). "Together, these data suggest that the transition into a CD44+/CD24− cell state can promote intra-tumor genetic heterogeneity, spur tumor evolution and increase tumor fitness." (PMID 28092266, 2017). "Using flow cytometry, CSCs can be distinguished from the bulk of the tumor by their expression of cell surface makers CD44 and CD24 (as a CD44(+)CD24(-/low) subpopulation) and based on the activity of ALDH1." (PMID 28270211, 2017). "We defined a parameter CD44/CD24 ratio to present the expression level of CD44 and CD24 and found that high CD44/CD24 ratio and ALDH1+ are both indicators for cancer malignancy, but play different functions during tumor progression." (PMID 29062075, 2017). "The CD44, CD24, HER2, and epithelial cell adhesion molecule (EpCAM) expression on BT474 and SK-BR-3 tumor cells was assessed by flow cytometry as a function of tumor treatment." (PMID 27835865, 2017). "We analyzed the clones’ CD44+/CD24- markers, in vitro sphere formation, and tumor formation in xenograft mice." (PMID 29137367, 2017). "As for the CD44+/CD24-/low cell fractions, one showed tumor-specific CNAs, while the other two were balanced." (PMID 28423035, 2017). "The hyaluronic acid receptor CD44 (a putative marker of ‘stemness’ in CRC) was also present and staining was detected in nearly all of the tumour cells we investigated." (PMID 28525976, 2017). "We investigated the mRNA and protein expressions of 84 genes known to be involved in tumor metastasis in rhBMP-2-treated MCF-7 cells; rhBMP-2 significantly downregulated Rb and E-cadherin and upregulated CD44 expression in MCF-7 cells." (PMID 28725489, 2017). "Like CD44, in cancer, CD24 is involved in cell-cell and cell-matrix junction and in cell migration, and is a significant marker for tumor prognosis as well as diagnosis." (PMID 28445439, 2017). "Expressions of SOX2, OCT4, WNT, NANOG, ABCG2 and ALDH1A1 was assessed both at transcriptional and translational levels from spheroids and sorted populations of CD44+/24− and ALDH+ cells of CT-TNBC tumor (CSC) versus the whole tumor." (PMID 28835684, 2017). "We showed that tumor cells were positive for all of these biomarkers, and that there was also moderate to strong expression of OPN, MAPK, MDM2, PEDF and CD44 in the stroma cells." (PMID 29029440, 2017). "Many OC labeled molecules, such as CA125, CD44, and HE4, contain Lewis y antigen structure, and Lewis y antigen modifies can enhanced the biological behaviors of tumor cells regulated by these proteins." (PMID 29296226, 2017).
tumor (continued). "The results indicate a differential stability of the CD133/Olig2 and CD44 GBM cell subpopulations with implications for the evolution of resistant subpopulations and tumor recurrence." (PMID 28241049, 2017). "High CD44/CD24 ratio was mainly in charge of self-renewal, proliferation, and tumor growth, while ALDH1+ represented a stronger capability for invasion and metastasis." (PMID 29062075, 2017). "Half of the mice injected with 100 CD44+CD24+ESA+ cells formed tumors, compared with 10000 triple-negative cells, which only 1 in 12 mice developed a tumor." (PMID 28245823, 2017). "An assumption of the presence in Ehrlich carcinoma (EC) population of stem cell, study of tumorigenic potential of CD44+ fraction and role of CD117+ cells in maintaining the tumor development requires an extra evidence." (PMID 28622715, 2017). "The HA receptor CD44 and receptor for hyaluronan-mediated motility (RHAMM) are highly expressed on the surface of tumor cells." (PMID 28155337, 2017). "While sorted cell populations ranged from 0.04% to 0.27% as expected in the four primary tumor regions, we detected a smaller proportion of EPCAM+CD44+CD49f+ cells in the lymph nodes ranging from 0.002% to 0.004%." (PMID 28487492, 2017). "The expressions of CD44, CD133, SOX2 and Nanog were correlated with histological grade and tumor stage for MEC of the palate respectively." (PMID 28262804, 2017). "In summary, our data strongly indicate that the transition into a CD44+/CD24− cell state can promote intra-tumor genetic heterogeneity, spur tumor evolution and increase tumor fitness." (PMID 28092266, 2017). "The primary tumor and the liver metastases of the mice burdening MDA-MB-231 cells were stained with antibodies targeting CD44, CD24 and ALDH1 and were imaged with fluorescent microscopy." (PMID 29062075, 2017). "Importantly, this increased Treg proliferation was not responsible for the expansion of the antigen-experienced memory CD4+ T cells (manuscript in preparation), as might be predicted by a study using another tumor model where Tregs primarily contributed to the CD137+CD44+CD4+ memory compartment." (PMID 27966460, 2017). "Within 2 weeks, both CD326+ CD44− cancer cells and CD326− CD44+ CAFs expanded by outgrowth from the initial tumor fragments." (PMID 28649646, 2017). "Next we confirmed role of CD44 in two EMT specific characteristics; tumor cell migration and invasion." (PMID 28279210, 2017). "Tumors generated by CD133+,CD44+ clone MU020 exhibited a large diffuse tumor, covering both left and right hemispheres, which suggests that this tumor harbors fast growing, highly invasive cells." (PMID 28241049, 2017). "Recent reports demonstrated that a hybrid epithelial/mesenchymal CD44+/CD24-/ALDH+ CSC subpopulation is more tumorigenic then its pure counterpart, although its role in metastasis and secondary tumor formation remains to be elaborated." (PMID 29348905, 2017). "Accordingly, we next looked at a potential relationship between 14q32 miRNAs expression and cancer stem cell markers, and we examined the expression of CD44, ABCG2, ALDH1A1, NANOG and c-MYC genes in 53 tumor samples." (PMID 27980227, 2017). "Many ovarian cancer marker molecules, such as CA125, CD44, and HE4, contain Lewis y antigen structure, and Lewis y antigen modifications also enhance the processes mediated by these molecules that promote tumor occurrence and development." (PMID 29296226, 2017). "In a previous study, we showed that adhesion of tumour cells on the reconstituted membrane matrix Matrigel increases when CD74 and CD44 are overexpressed." (PMID 29190904, 2017). "In PC, CSCs have initially been identified by being characterized as CD44+CD24+ESA+cells and having the ability to form tumors at a much higher frequency than the bulk tumor." (PMID 28245823, 2017).